TRPA1 (transient receptor potential cation channel subfamily A member 1)
Diseases named in the same sentence as TRPA1 in open-access papers (continued):
Sharing a sentence is not in itself a finding about the gene and the disease.
Pruritus (continued). "Within this integrated microenvironment, specific TRP channels, notably TRPA1, TRPV1, TRPV3, and TRPV4, exhibit a remarkable ability to simultaneously influence both fibrotic and pruritus-related signaling pathways." (PMID 41596464, 2026). "In this review, we discuss the role of TRP channels TRPA1, TRPV1, TRPV2, TRPV3, TRPV4, TRPM8, and TRPC3/4 in acute and chronic pruritus." (PMID 38139833, 2023). "The discovery of Hashimoto provided a new direction for researching the mechanism of Periostin-mediated pruritus in PS through the activation of TRPV1 and TRPA1." (PMID 37705977, 2023). "These gene coexpression results show thatTmem100-,Trpa1- andMrgpra3-positive neurons should be the main neuron population for AEW itch and that TMEM100 facilitates TRPA1 function and AEW itch sensation mainly in this population of DRG neurons." (PMID 36514220, 2022). "To further investigate the relationship between TMEM100 and TRPA1 and the possible treatment effect of AEW itch through modulation of TMEM100, we synthesized adeno-associated virus (AAV) vectors containingTmem100-shRNA." (PMID 36514220, 2022). "Thus, attenuation of TRPA1 and TRPV1 expression and their surface trafficking, plus inhibition of itch-related neuropeptide release from pruritic nerve would underlie the observed anti-pruritic activity of BoNTs in animal models of chronic itch and in patients with itch conditions." (PMID 34276687, 2021). "There have been reports that TRP channels other than TRPV3, such as TRPV1/4, TRPA1, and TRPM6/7 contribute to pruritus." (PMID 29140280, 2017). "In our previous study, we evaluated the clinical and histopathological characteristics of patients with post-burn pruritus and discovered increased expression of TRPV3, TRPV4 and TRPA1." (PMID 29140280, 2017). "These receptors, which include GPCRs, cytokine receptors, and Toll-like receptors (TLRs), facilitate the opening of ion channels, particularly TRP channels like TRPV1 and TRPA1, and mediate receptor-operated calcium entry (ROCE), leading to the generation of pruritus action potentials." (PMID 41596464, 2026). "Studies have shown that the expression of TRPA1 in the scar tissue of patients with burn scar pruritus is higher than that of patients without pruritus, especially in mast cells." (PMID 37705977, 2023). "TRPA1 and TRPV1 are also considered to play a key role in the AEW‐induced chronic itch behavior." (PMID 37452499, 2023). "Burn patients with pruritus had increased TRPA1 mRNA compared to burn patients without pruritus, and TRPA1 mRNA expression showed a positive correlation with the intensity of post-burn pruritus." (PMID 37555911, 2023). "In the present study, we mainly focused on the role of TMEM100 in the AEW itch model and the regulatory mechanism of TMEM100 in TRPV1 and TRPA1 functional changes to clarify the mechanism of the TRPV1 and TRPA1 functions modulated by TMEM100 during dry skin-induced itch." (PMID 36514220, 2022). "Furthermore, the activation of TRPA1, oxidative stress, and extracellular regulated protein kinase (ERK) signaling were involved in low-dose formalin-induced itch in mice." (PMID 33681255, 2021). "Thus, we demonstrated that the zinc/TRPA1/GPR39 axis played a critical role in Zn2+-induced acute and chronic itch in mice." (PMID 35095413, 2021). "Our findings that IMQ-induced itch was attenuated, but not abolished, in Trpa1-/- mice supports additional mechanisms for IMQ-evoked itch in this species." (PMID 29561265, 2018). "Treatment of mouse skin with 2,4-dinitrochlorobenzene (DNCB), for example, activates TRPA1 and generates an AD-like phenotype, and mice lacking TRPA1 have decreased dermatitis and pruritus scores, Th2 cytokines, epidermal hyperplasia, ear thickness, mast cell and macrophage infiltration." (PMID 36430783, 2022).
Pruritus (continued). "Nevertheless, since evidence showed that the TRPA1 is crucially involved in the pathogenesis of AD and ACD, the pharmacological inhibition of the channel could be a valuable complementary strategy for local control of skin inflammation and pruritus observed in both diseases." (PMID 33802836, 2021). "In the AEW itch model, the itch-facilitating effect of TMEM100 is achieved mainly through the modulation of TRPA1 but not TRPV1." (PMID 36514220, 2022).
neuropathy (32 papers, 2008 to 2025). A disorder affecting the nervous system that manifests with pain, tingling, numbness, and/or muscle weakness. "The sensitization of TRPV1 (transient receptor potential vanilloid 1) and TRPA1 (transient receptor potential ankyrin) channels, driven by PKCε activation, has been linked to paclitaxel-induced neuropathy, manifesting as cold and mechanical allodynia." (PMID 39598298, 2024). "TRPA1 is expressed in nervous tissue, where it participates in the genesis of nociceptive signals in response to noxious stimuli and mediates mechanical hyperalgesia and allodynia associated with different neuropathies." (PMID 33379368, 2020). "Based on clinical observations of chemo-induced neuropathy, we hypothesized that bioaccumulation of aluminum may be associated with several aspects of neurotoxicity, and that TRPA1 activation facilitates induction of cold hyperalgesia and allodynia." (PMID 25928068, 2015). "Mechanistically, DJ-1 in primary sensory neurons regulated this hypersensitivity and neuropathy via TRPA1 signalling." (PMID 39486088, 2025). "TRPA1 antagonists showed some effectiveness in rats with milder neuropathy, indicating its role in moderating milder neuropathy." (PMID 40787071, 2025). "The participation of TRPA1 in neuropathic pain was also demonstrated in spinal nerve ligation and chemotherapy-induced neuropathy rodent models." (PMID 40430479, 2025). "NCS1 and TRPA1 have a role not only in cancer but also in the development of neuropathy, a reason to carry out tests in neuronal models such as SH-SY5Y cells." (PMID 38564162, 2024). "TRPA1 antagonists reduced pain in less severe neuropathic pain models and showed some effectiveness in patients with milder neuropathy." (PMID 37893054, 2023). "In a recent study, systematic therapy with Sigma-1 receptor (an endoplasmic reticulum chaperone) antagonists reduced painful symptoms in an oxaliplatin-induced neuropathy mice model through regulating TRPA1." (PMID 37893054, 2023). "PTX-induced neuropathy involves TRPA1 activity through an increase in functional expression and is regulated by PKA and PKC signaling." (PMID 36098890, 2023). "This is indicated by the observation that a low intrathecal dose of a TRPA1 antagonist effectively reduced hypersensitivity in animals with a spinal nerve ligation-induced neuropathy." (PMID 30388732, 2018). "Concerning potential clinical applications, a promising experimental animal finding is that a brief prophylactic treatment with a TRPA1 antagonist before start of the chemotherapy effectively prevented the development of the chemotherapy-induced neuropathy." (PMID 30388732, 2018). "After the subcutaneous injection of the selective TRPA1 antagonist HC-030031, the cold allodynia is substantially suppressed, and the effect of cancer-induced neuropathy is transiently reversed in a dose-dependent manner." (PMID 30510606, 2017). "A novel and a promising model of cancer-induced neuropathy was established, and the role of TRPA1 and CGRP in pain transduction was examined." (PMID 30510606, 2017). "The effect of Goshajinkigan on neuropathy through inhibition or stimulation of TRPA1, TRPM8, and TRPV1 channels in oxaliplatin-induced neuropathy rat model was recently investigated." (PMID 29326595, 2017). "Pharmacological inhibition of TRPA1 or knockout of Trpa1 gene significantly alleviates the OP-induced neuropathy." (PMID 28894590, 2017). "TRPA1 is a Ca2+-permeable ion channel involved in many sensory disorders such as pain, itch and neuropathy." (PMID 28332600, 2017). "In conclusion, the current study provides compelling evidence that TRPA1 mediates OPIDN and that TRPA1 is an effective therapeutic target for the neuropathy." (PMID 28894590, 2017). "In the case of chemotherapy-induced neuropathy, TRPA1 appears to be activated indirectly by platin-induced alteration of redox state." (PMID 27983625, 2016).
neuropathy (continued). "Together, these findings are consistent with the notion that TRPA1 is central for the development of several common and clinically important classes of painful metabolic or pharmacologically induced neuropathies." (PMID 24167592, 2013). "TRPA1 has a main role in the development and maintenance of cold and mechanical hypersensitivity in chronic inflammatory diseases and neuropathies." (PMID 24288041, 2011). "Although these data suggest an important role for TRPA1 in the maintenance of pain following neuropathy, the endogenous mediators and/or mechanisms responsible for TRPA1 activation in this case are less clear." (PMID 18954467, 2008). "TRPA1 has been presented as a candidate to mediate inflammatory mechanical hyperalgesia as well as cold hyperalgesia under inflammatory conditions; indeed HC-030031, a TRPA1 selective antagonist, attenuates inflammatory- and neuropathy-induced mechanical hypersensitivity." (PMID 33379368, 2020). "In the same line, bortezomib-induced neuropathy is characterized by cold, mechanical allodynia and hypersensitivity to a TRPA1 agonist; this effect could be blocked by TRPA1 antagonist HC-03003 or the antioxidant α-lipoic acid." (PMID 31197115, 2019). "While immunocytochemical and molecular biological evidence for amygdaloid TRPA1 expression in neuropathic animals is still missing, this pharmacological finding suggests that nerve injury induces oxidative stress and potentially amygdaloid expression of TRPA1 in neuropathy." (PMID 30388732, 2018). "In experimental animal studies, blocking TRPA1 has effectively attenuated cold and mechanical allodynia induced by anti-cancer drugs, such as paclitaxel or oxaliplatin, indicating that TRPA1 is involved in chemotherapy-induced neuropathy." (PMID 30388732, 2018). "Additionally, several studies demonstrated that pharmacological inhibition of TRPA1 with HC-030031, a selective TRPA1 antagonist, attenuated inflammatory- and neuropathy-induced mechanical hypersensitivity in rodents." (PMID 30353098, 2018). "TRPA1 is also a key participant in two common models of pathological chronic pain, streptozotocin-induced diabetic neuropathy and chemotherapy-induced neuropathy." (PMID 27983625, 2016). "This experiment may open the window for a direct evidence to investigate the correlation among the role of TRPA1, aluminum accumulation and oxaliplatin-induced neuropathy." (PMID 25928068, 2015). "Expression of TRPA1 mRNA and protein was also activated in the Al-induced neuropathy model." (PMID 25928068, 2015). "Concerning this, chronic inhibition of TRPA1 might be expected to reduce neuropathy in diabetes." (PMID 31547502, 2019). "An increase in the systemic LPS level may enhance pain in diabetes and advance development of neuropathy, since LPS is a TRPA1 agonist and it enhances the effect of other TRPA1 agonists such as 4-hydroxynonenal, the concentration of which is increased in diabetes." (PMID 30388732, 2018). "Notably, we found that those NTE inhibitors also exerted significant agonistic activity on TRPA1 channels, which could explain how they aggravate the OP-induced neuropathy and is consistent with the major role of TRPA1 in OPIDN." (PMID 28894590, 2017). "This is the first study to describe sensitization of TRPV1 and TRPA1 and/or TRPM8 in a model of oxaliplatin induced neuropathy, the role of cAMP in mediating the sensitization, and the effectiveness of a CB2 agonist in mitigating it." (PMID 21106058, 2010). "The panel application ‘Inherited neuropathies or pain disorder v1.36’ was informed by the NIHR Bioresource (100 000 genomes), our functional studies and includes all the tier 1 pain genes in this paper and TRPA1." (PMID 36895957, 2023). "Our results show that TRPA1 is the principal target for MG in sensory neurons but not in pancreatic β-cells and that activation of TRPA1 by MG produces a painful neuropathy with the behavioral hallmarks of diabetic neuropathy." (PMID 24167592, 2013).
neuropathy (continued). "Finally, in paclitaxel-induced neuropathy TRPV1 and TRPA1 channels are sensitized, and blockage by the TRPA1 selective inhibitor, HC-030031, attenuates paclitaxel-induced mechanical, heat, or cold hypersensitivity." (PMID 24288041, 2011). "A study regarding the involvement of TRPA1 in the relationship between cold exposure and chemotherapy-induced neuropathy has not been completed yet (NCT03329131), which also applies to a trial which investigates genetic variations in platinum-based chemotherapy-induced neuropathy (NCT03252834)." (PMID 31547502, 2019). "Therefore the major role between TRPM8 and TRPA1 for cold sensing in oxaliplatin-induced neuropathy is not clearly identified and further studies are needed." (PMID 25928068, 2015). "However, Ding and colleagues reported that tested organophosphates activated TRPA1 (also a Ca2+ permeable non-selective cation channel), increased the influx of Ca2+ while TRPA1 antagonists significantly relieved organophosphate-induced neuropathy models." (PMID 38917121, 2024). "Thus, direct protection of neuronal cells by components of GJG, rather than modulation of the TRPA1 channel, could to be involved in the amelioration of the later phase neuropathy." (PMID 26542342, 2015).
Arthritis (28 papers, 2014 to 2025). Inflammation of a joint. "We investigated the role of TRPA1 in mediating the differences in blood flow caused by cold exposure in animals with 2-week mono-arthritis." (PMID 26754745, 2016). "Although TRPA1-deficient mice are also valuable tools to investigate the role of this receptor in vivo, only few arthritis studies have been performed with these." (PMID 26746673, 2016). "The activation of TRPA1 in neutrophils has been linked to arthritis, although it remains unclear if this is due to a direct role of TRPA1 in neutrophils or an indirect effect of non-immune TRPA1." (PMID 34768891, 2021). "Furthermore, Elizabeth and other studies also showed that TRPA1 mediates arthritis pain caused by cold environmental stimulation." (PMID 35295475, 2021). "In models of arthritis, TRPA1 has been linked both to joint inflammation and hyperalgesia." (PMID 33193423, 2020). "GYY4137 caused significant reduction of the arthritis on day 5 in TRPA1 WTs." (PMID 31551776, 2019). "Our findings are in keeping with the concept that pharmacological manipulation of peripheral TRPA1 channels may attenuate changes in blood flow and hyperalgesia associated with arthritis, particularly in cold conditions." (PMID 26754745, 2016). "TRPA1 mediates inflammatory pain and plays a significant role in the development of arthritis, including the model of MIA-induced arthritis, as shown in knockout mice and TRPA1 antagonists’ treatment." (PMID 38132938, 2023). "In one study, cold exposed CFA arthritis mice developed bilateral pain sensitivity in their knee joints, which was dependent on the cold sensor, TRPA1." (PMID 36926330, 2023). "In the present study, we demonstrate, for the first time, that TRPV1+ and TRPA1+ DRG nociceptive neurons are activated in TiO2-induced arthritis." (PMID 36677929, 2023). "HMC treatment reduced the basal neuronal activation caused by TiO2-induced arthritis as well as the responsiveness of TRPV1+ and TRPA1+ DRG neurons, which are two important subsets of nociceptive neurons." (PMID 36677929, 2023). "In most arthritis studies, TRPA1 was reported to be increased and acted as a promoter of joint destruction, mediating inflammatory and catabolic effects, oxidative stress, apoptosis, edema, and pain." (PMID 37006615, 2023). "DMTS attenuated vascular inflammation characterized by paw volume, arthritis score, and plasma extravasation rate in both TRPA1 WT and KO mice." (PMID 35745590, 2022). "Together, these findings highlight the role of TRPA1 as a potential mediator and novel drug target in various types of arthritis." (PMID 35562920, 2022). "TRPA1 WT and KO mice with serum transfer arthritis showed elevated MPO activity 2 and 6 days after challenge irrespective of vehicle or DMTS treatment compared to the baseline enzyme activity." (PMID 35745590, 2022). "Serum-transfer arthritis elevated the plasma extravasation both 2 and 6 days after serum treatment compared to the baseline values in TRPA1 WT and KO animals administered a vehicle or DMTS." (PMID 35745590, 2022). "Mechanical hyperalgesia, the arthritis score, and damage to cartilage were mitigated in TRPA1 WT subjects." (PMID 35745590, 2022). "Auranofin, which improves arthritis symptoms, including painful joints, and is widely used for the treatment of RA, has been shown to activate the human isoform of TRPA1." (PMID 35562920, 2022). "In conclusion, we demonstrated that DMTS allayed paw swelling and plasma extravasation in the K/BxN serum-transfer arthritis independently from the TRPA1 ion channel." (PMID 35745590, 2022). "In a CFA-induced arthritis model, Trpa1-/- mice exhibited reduced arthritis symptoms and myeloperoxidase activity, as a reflex of neutrophil activation, in the ankle joints." (PMID 34768891, 2021). "TRPA1 is functionally expressed in synovial cells and fibroblasts that mediate the production of arthritis-related proinflammatory factors or cytokines to lessen pain and to slow the progression of arthritis." (PMID 33810314, 2021).